EGFR (epidermal growth factor receptor)
Diseases named in the same sentence as EGFR in open-access papers (continued):
Sharing a sentence is not in itself a finding about the gene and the disease.
tumor (continued). "Tumor cell killing and IFNγ secretion did not correlate with the EGFR expression levels of the different cell lines." (PMID 41341587, 2025). "EGFR is overexpressed in many CRCs, particularly those without RAS mutations, and plays a key role in tumor cell proliferation, survival, and migration." (PMID 41454126, 2025). "For example, targeting mitogen-activated protein kinase (MAPK) pathway utilizing EGFR/MEK/BRAF inhibitors was shown to induce the expression of tumor neoantigens, promote the infiltration of CD8+ T cells to the tumor site and block the canonical oncologic signaling pathways." (PMID 40342408, 2025). "Among the synthetic agents evaluated in vivo, Zotarolimus and 20(S)-Protopanaxadiol (PPD) exhibit the strongest therapeutic potential based on their ability to suppress key oncogenic pathways —including EGFR, VEGF, NF-κB, and MAPK/ERK—and significantly reduce tumor burden in CRC xenograft models." (PMID 41149466, 2025). "Moreover, in patient-derived organoids of K-Ras-driven colorectal cancers, EGFR activity is essential to promote ERK phosphorylation and tumor cell proliferation." (PMID 41132131, 2025). "In vivo, pyrotinib induced significant tumor regression in EGFR-high CN GC derived xenografts, whereas no inhibition was observed in EGFR‐low CN models." (PMID 40830980, 2025). "Patient ACCC_CRC_15, the only MSI sample in this cluster, also showed an overall trend of under‐activation in the majority of estimated pathway and TF activities, whereas the EGFR signaling cascade and MYC TF were found significantly over‐activated in this POLE‐mutant tumor." (PMID 39876058, 2025). "Circulating tumor cells (CTCs) (4′,6-diamidino-2-phenylindole (DAPI) + glial fibrillary acidic protein (GFAP) + epidermal growth factor receptor (EGFR) + CD45−CD66b−) zero-converted after therapy (16 CTCs in 7.5 ml blood detected on day −9 versus zero CTCs on day +190)." (PMID 40016450, 2025). "Initial IF surveys of solid lung tumor regions showed little HIV replication, as indicated by the lack of HIV p24 expression, and reduced EGFR expression compared to non-tumor regions." (PMID 40710199, 2025). "This modified combination regimen may be a promising therapeutic option for EGFR‐mutant NSCLC patients with TKI resistance, especially those with PD‐L1‐positive tumours." (PMID 39715697, 2025). "Furthermore, the combination treatments (EGFR and TERT or EGFR and GABPB1) led to even greater tumor growth inhibition than the single treatments." (PMID 40463649, 2025). "Reduced tRNA m7G modification on tRNAs by knocking down of METTL1 severely impaired the translation of the tumour-related genes and pathways, including cell-cycle regulator Cyclin D3 (CCND3), epidermal growth factor receptor (EGFR), phosphatidylinositol 3-kinase (PI3K) and protein kinase B (AKT)." (PMID 39723662, 2025). "Additionally, Car-NK cells targeting EGFR demonstrated enhanced cytotoxicity and apoptosis induction in SCC cell lines and primary HNSCC tumor cells." (PMID 41511327, 2025). "By inhibiting both EGFR and PI3K/mTOR pathways, this approach may reduce tumor cell viability more effectively and delay the development of resistance." (PMID 40650170, 2025). "Clinically, 89Zr-immuno-PET has demonstrated significant utility in oncology, particularly for imaging tumours overexpressing human epidermal growth factor receptor 2 (HER2), epidermal growth factor receptor (EGFR), and vascular endothelial growth factor (VEGF)." (PMID 40574051, 2025). "Heterogeneous EGFR expression has been observed: approximately 10%–20% of cSCC patients exhibit low EGFR expression (IHC score 1+) or are negative in tumor tissues, potentially rendering them unresponsive to EGFR/CD3 bispecific antibodies." (PMID 41333481, 2025). "SRC expression in HER2-positive tumor cells has been found to be consistent with HER2 expression, and evidence suggests that SRC may act as a link between EGFR and MET." (PMID 40181988, 2025).
tumor (continued). "The tumor was negative for epidermal growth factor receptor (EGFR), anaplastic lymphoma kinase (ALK), ROS proto-oncogene 1 (ROS1) mutations and demonstrated a programmed death-ligand 1 (PD-L1) expression of 60%." (PMID 41304963, 2025). "Notably, FAP exhibited a positive correlation (r ≈ 0.4, p < 0.01) with genes involved in angiogenesis and tumor microenvironment remodeling, including VEGFA, HIF1α, and EGFR." (PMID 40430845, 2025). "Strategies under investigation include combination therapies with other immune modulators (e.g., LAG-3, TIGIT inhibitors), targeted therapies (e.g., EGFR or KRAS inhibitors), and epigenetic modulators that reprogram the tumor microenvironment to be more immunogenic." (PMID 41584608, 2025). "Similar to NSCLC, in GC, the EGFR, Wnt, and YAP pathways promote tumor progression." (PMID 41415714, 2025). "In contrast, several tumor-promoting pathways, such as the mTOR signaling pathway, PI3K-Akt signaling pathway, EGFR tyrosine kinase inhibitor resistance, TGF-β signaling pathway, and Ras signaling pathway, were significantly downregulated following the ER-Cy-poNO2-mediated phototherapy." (PMID 40283929, 2025). "Integrating scRNA‐seq, next‐generation sequencing (NGS), and multiplex immunofluorescence, our study provides new insights into the potential roles of OPC‐like subpopulations—particularly those expressing EGFR and PDGFRA—in tumor initiation, progression, and lineage transitions." (PMID 41036308, 2025). "It was reported that EGFR triggers endoplasmic reticulum stress and activates the UPR pathway through downstream signaling pathways such as RAS/MAPK and PI3K/AKT, inhibiting cell apoptosis and promoting tumor cell survival and drug resistance." (PMID 40877231, 2025). "Beyond its role in modulating EGFR-dependent signaling pathways, the CD147–CD44 complex also exerts significant influence over localization and stabilization of metabolic transporters that sustain tumor aggressiveness." (PMID 41479915, 2025). "that integrated the EGFR inhibitor erlotinib with the MET inhibitor PF04217903 in a c-SRC (Cellular Sarcoma Kinase) expressing cell line demonstrated a significant reduction in cell viability and tumor volume." (PMID 40881676, 2025). "Decorin and lumican can suppress growth factor signaling (e.g., TGF-β and EGFR), while biglycan may promote inflammatory signaling through TLR2/4, underscoring their dual tumor-suppressive and tumor-promoting roles." (PMID 41228294, 2025). "The tumor showed no epidermal growth factor receptor (EGFR) expression or anaplastic lymphoma kinase (ALK) rearrangement and was characterized by bilateral pulmonary involvement without distant metastases." (PMID 40255775, 2025). "In EGFR-mutant NSCLC, recent findings indicate that chromatin reprogramming, and transcription factors dynamically rewire transcriptomic landscape under therapeutic pressure, allowing tumor cells to evade anti-cancer treatment." (PMID 40414926, 2025). "Thus, co-treatment with a combination of three inhibitors for EGFR, MET, and FGFR reduces the tumor size of subcutaneous and intracranial GB xenografts in mice to a greater extent than treatment with two inhibitors for EGFR and MET." (PMID 41516252, 2025). "Our results showed that individual inhibition of EGFR did not increase the radiation response in tumor cells, proving that tumoral heterogeneity and adaptability can overcome the individual targeting of one RTK." (PMID 40821315, 2025). "It has also been reported to induce oxidative stress, inflammation, and oncogene activation, including the epidermal growth factor receptor (EGFR) pathway, which plays a key role in tumour progression and is therefore a target for investigation under acute exposure conditions." (PMID 40559957, 2025).
tumor (continued). "In conclusion, EGFR overexpression potentially stimulates the expression of PCBP2 through transcriptional regulation, and PCBP2 subsequently identifies GGGU motif-containing miRNAs to facilitate their secretion via sEVs, thereby promoting tumor angiogenesis." (PMID 39816681, 2025). "Additionally, genipin decreases tumor cells’ resistance by lowering the expression of EGF, EGFR, PKB, and GSK-3β." (PMID 40656954, 2025). "Collectively, the assessment of PD‐L1, PD‐L2, and EGFR expression in naive tumor specimens does not accurately reflect the expression of these molecules at recurrence in patients with HNSCC." (PMID 40156197, 2025). "Additionally, its structural similarity to EGF enables it to bind and activate EGFR downstream signaling pathways, triggering epithelial-mesenchymal transition (EMT) and enhancing tumor cell metastatic potential." (PMID 40904507, 2025). "A case report on a young female patient (with EGFR amplification and multifocal progression of the disease after surgery, RT, TMZ, and bevacizumab) who was treated with Osimertinib daily for one month, showed a complete response in one of the tumor sites." (PMID 40358199, 2025). "In this study, we investigated the differently expressed miRNAs between EGFR-mutant and wild type NSCLC exosomes, explored mechanisms of the miRNA expression, regulation, and promotion of apoptosis, and also studied the anti-tumor function of the miRNA inhibitor in humanized mouse models." (PMID 40002895, 2025). "Dual EGFR and PI3K inhibition in TNBC with EGFR amplification and PI3K aberrations act synergistically in reducing cell viability, as well as inducing apoptosis in vitro, and reducing tumor growth in vivo." (PMID 40501689, 2025). "The upregulation of EGFR leads to autophosphorylation of EGFR, subsequently activating multiple oncogenic signaling cascades, including the Ras/MAPK, PI3K/AKT, and STAT pathways, which collectively accelerate malignant tumor biological functions." (PMID 40362183, 2025). "EGFR alterations drive aberrant cell proliferation and survival by activating downstream pathways such as RAS/RAF/MEK/ERK and PI3K/AKT, which confer resistance to therapies and promote tumor growth." (PMID 39936963, 2025). "As far as we are aware, no information about the role of Nano-Gefitinib against EGFR-mediated macrophage reprogramming in the EAC tumor has been published in the literature." (PMID 41304988, 2025). "The tumor showed N-MYC copy number gain but no alterations in EGFR as often seen in N-MYC subtype pediatric HGG." (PMID 41155159, 2025). "Notably, some receptors turned off via the CIN85 pathway, including EGFR, FGFR, and RTKs, are important for tumor growth." (PMID 40990523, 2025). "In some contexts, NRF2 activation can prevent tumor formation or have no impact on tumor formation but provide an advantage in response to platinum therapy or protect against EGFR inhibition." (PMID 40334547, 2025). "Furthermore, a PYCR1 chemical inhibitor, PYCR1-IN-1, significantly suppressed the 3D tumor spheroid formation driven by both TLR and EGFR signaling." (PMID 41254241, 2025). "Recruiting T cells near the tumor, followed by tumor cell death by activated T cells, may also be achieved by CD3 x EGFR bispecific antibodies and PD-L1-targeting ADCs, aiming for enhanced T cell responses." (PMID 40407689, 2025). "Recently, wedemonstrated the high efficiency of the therapy based on the recombinantSLURP-1 in controlling SCC cell growth and metastasis in vivo.The anti-tumor effect of SLURP-1 was mediated through interaction with bothα7-nAChR and the epidermal growth factor receptor (EGFR)." (PMID 40264586, 2025).
tumor (continued). "Furthermore, beer contains malt-derived compounds, pigments, and heterocyclic amines, which can activate the epidermal growth factor receptor (EGFR)-MAPK and PI3K-Akt signaling pathways, thereby promoting tumor cell proliferation and survival." (PMID 39940440, 2025). "Our results demonstrate that, through its deubiquitinating activity, USP11 enhances the stability of EGFR and TRAF6, crucial mediators in these pathways, ultimately promoting CRC tumorigenesis, cell migration, proliferation, colony formation, and 3D tumor spheroid formation." (PMID 41419456, 2025). "While most tumor meta-programs exhibited melanocytic differentiation (high MITF and CTNNB1), two meta-programs-Respiration and Stress-expressed dedifferentiation markers including AXL, SOX9, EGFR and NGFR." (PMID 40890106, 2025). "Dysregulation of PTTG genes may inhibit cell cycle progression and counteract the proliferative effects of EGFR/KRAS signaling, leading to reduced tumor growth." (PMID 40877987, 2025). "EGFR-activity subtypes characterized by accumulating expression of AREG and concurrently reduced expression of epithelial marker EpCAM promote de-differentiation towards EMT, local invasion, tumor budding, and are correlated to worsened OS." (PMID 40121428, 2025). "Additionally, VVD-844 inhibited tumor growth in EGFRmut PDX models, including models derived from patients that developed resistance to the third generation EGFR inhibitor, osimertinib." (PMID 41066541, 2025). "In other words, even after the traditional selection based on RAS and BRAF and tumor sidedness, approximately one-third of patients do not respond to EGFR-inhibition, indicating that additional molecular escape mechanisms limit therapeutic efficacy." (PMID 40940901, 2025). "EGFR overexpression can drive astrocyte proliferation and induce an AC-like program in GBM, further implying that PANoptosis enrichment is related not only to tumor progression but also to the distribution of cellular states within GBM." (PMID 39901195, 2025). "LGALS3 promoted tumor progression, invasiveness, and immune suppression, and blocking LGALS3‐ANXA2 has been documented to initiate cell apoptosis by suppressing all downstream EGFR signaling pathways." (PMID 40776410, 2025). "This review provides an integrated overview of GBM’s pathophysiology, highlighting key mechanisms such as neuroinflammation, genetic alterations (e.g., EGFR, PDGFRA), the tumor microenvironment, microbiome interactions, and molecular dysregulations involving gangliosides and sphingolipids." (PMID 40868137, 2025). "Inhibition of BRAF may lead to reactivation of MAPK signalling, including EGFR and MEK, which are considered to be a dominant driver in many tumour types." (PMID 38773787, 2025). "Despite clinical success in other neoplasms, targeting EGFR has not yielded significant benefits for patients with GBM." (PMID 40581663, 2025). "We thus suspect that EGFR TKi-based therapy might be ineffectual or even harmful as it might transiently activate ERK, and in turn fuel tumour stemness and self-renewal." (PMID 40764669, 2025). "To investigate whether inhibition of osimertinib-tolerant/persister cells by sorafenib could affect tumor growth, we used BEM-4 cells, another mouse clonal cell line expressing mutant EGFR we have generated." (PMID 40846697, 2025). "Conversely, activation of EGFR/KRAS pathways may suppress PTTG gene expression, thereby modulating cell cycle dynamics and limiting tumor progression." (PMID 40877987, 2025). "Intragenic mutations in EGFR and PDGFRA produce functionally active variants that not only enhance cell division, but also modify the TME, promoting tumor invasion and facilitating angiogenesis." (PMID 40868137, 2025). "In conclusion, this study provided prospective paired tumor tissue and plasma samples, allowing for a more comprehensive and accurate analysis of GPS at the first-line treatment failure of osimertinib for EGFR-mutant locally advanced or metastatic NSCLC patients." (PMID 41326340, 2025).
tumor (continued). "However, BL-B01D1, a BsADC targeting EGFR and HER3, has shown promising anti-tumor efficacy in clinical trials." (PMID 40057807, 2025). "Evidence suggests that, under the selective pressure of EGFR-TKI treatment, distinct tumor cell subpopulations may undergo selective expansion, allowing subclones harboring resistance-associated mutations to persist and emerge as dominant tumor clones." (PMID 40003951, 2025). "Since EGFR-activating mutations are also prevalent in LUAD, we performed similar analyses between mutation-positive and -negative samples in this tumor type." (PMID 39959305, 2025). "Moreover, BF inhibited the phosphorylation levels of EGFR, RAF, MEK, and ERK in tumor tissues, further corroborating its inhibitory effects on the RAS/RAF/MEK/ERK signaling pathway." (PMID 40883741, 2025). "The failures of targeting EGFR are largely attributed to GBM heterogeneity with intertwined oncogenic signaling, dynamic switching between tumor subtypes, and an immuno-suppressive tumor microenvironment." (PMID 40678238, 2025). "Furthermore, the recruitment of EGFR to the COX‐2 promoter increases COX‐2 expression, which can also contribute to tumour progression." (PMID 40211955, 2025). "Besides, epigenetic alterations mediated by miRNAs have been shown to contribute to the physiology of GBM, by acting on the already described genes and pathways (EGFR, PI3K, etc.)and other key cellular processes essential for tumor survival." (PMID 40813676, 2025). "PTTG genes, known for their involvement in cell cycle regulation, may synergize with EGFR and KRAS signaling pathways to promote tumor growth and aggressiveness." (PMID 40877987, 2025). "The combination of Defactinib and the EGFR-TKI gefitinib significantly reduces tumor volume in athymic nude mice bearing PC9GR tumors and decreases the expression levels of p-FAK, p-AKT, and p-ERK in tumor tissue." (PMID 41008540, 2025). "The results revealed elevated epidermal growth factor receptor (EGFR) signaling pathway at the tumor borders, primarily in tumor cells, in the two non-responders (#41 and #56) in arm Cam+TPF compared to the non-responders (#59 and #65) in arm Cam." (PMID 39889711, 2025). "Although the biological implications remain unclear, simultaneous activation of the EGFR and FGFR signaling axes could contribute to tumor heterogeneity and influence therapeutic response." (PMID 41301039, 2025). "It is important to clarify that not all of these proteins act exclusively as tumor suppressors; some, such as EGFR, STAT3, SRC, and HSP90AA1, are oncogenic drivers whose inhibition can suppress cancer growth." (PMID 41150809, 2025). "Moreover, EGFR activation induces RAS phosphorylation and subsequent activation, thereby initiating a downstream RAF→MEK→ERK signaling cascade that promotes tumor cell proliferation and anti-apoptotic signaling." (PMID 40883741, 2025). "Tumor localization studies were conducted using MC lines expressing human rather than murine PSMA or EGFR due to the specificity of our Abs and CAR." (PMID 39904797, 2025). "EGFR-ERK signaling stabilizes PDL-1 expression, suggesting that the modulation of the tumor microenvironment (TME) could represents an alternative strategy to impairs GBM progression." (PMID 39966897, 2025). "The previous studies suggest that FTO might contribute to tumor growth; hence, we performed gene and protein expression analysis on NSCLC cell lines to examine whether FTO is upregulated in EGFR-TKI-resistant cell lines." (PMID 40722726, 2025). "Three of these cases also exhibited concurrent alterations in the tumour suppressor genes ARID1A, NF1, or RB1, suggesting even poorer prognosis and a need for more intensive follow‐up or more aggressive interventions beyond EGFR TKI monotherapy." (PMID 41015991, 2025).